COX4I1 (cytochrome c oxidase subunit 4I1)
Description:
Component of the cytochrome c oxidase, the last enzyme in the mitochondrial electron transport chain which drives oxidative phosphorylation. The respiratory chain contains 3 multisubunit complexes succinate dehydrogenase (complex II, CII), ubiquinol-cytochrome c oxidoreductase (cytochrome b-c1 complex, complex III, CIII) and cytochrome c oxidase (complex IV, CIV), that cooperate to transfer electrons derived from NADH and succinate to molecular oxygen, creating an electrochemical gradient over the inner membrane that drives transmembrane transport and the ATP synthase. Cytochrome c oxidase is the component of the respiratory chain that catalyzes the reduction of oxygen to water. Electrons originating from reduced cytochrome c in the intermembrane space (IMS) are transferred via the dinuclear copper A center (CU(A)) of subunit 2 and heme A of subunit 1 to the active site in subunit 1, a binuclear center (BNC) formed by heme A3 and copper B (CU(B)). The BNC reduces molecular oxygen to 2 water molecules using 4 electrons from cytochrome c in the IMS and 4 protons from the mitochondrial matrix.
Synonyms: COX IV-1; COX4; COX4-1; COXIV; COXIV-1; MC4DN16
Tractability: Small molecule: a structure with a bound ligand is known. Antibody: UniProt predicts a signal peptide or a membrane-spanning region. PROTAC: ubiquitination databases record sites on it; its protein half-life has been measured.
Gene: Protein-coding gene on chromosome 16 (85,798,633 to 85,807,068, forward strand). Ensembl gene ENSG00000131143.
Subcellular location: Mitochondrion inner membrane
Subcellular location (Human Protein Atlas): Mitochondria
Pathways (Reactome):
Metabolism: Complex IV assembly; Respiratory electron transport
Cellular responses to stimuli: Cytoprotection by HMOX1
Metabolism of proteins: Mitochondrial protein degradation
Gene Ontology:
Molecular function: protein binding; cytochrome-c oxidase activity
Biological process: cellular respiration; generation of precursor metabolites and energy; mitochondrial electron transport, cytochrome c to oxygen; oxidative phosphorylation; proton transmembrane transport; response to nutrient
Cellular component: membrane; mitochondrial inner membrane; mitochondrial membrane; mitochondrion; respiratory chain complex IV; mitochondrial intermembrane space; cytosol
Genetic constraint (gnomAD): Loss-of-function variants: 18 observed, 23.21 expected, observed/expected ratio (o/e) 0.78, 90% interval 0.54 to 1.15. The upper end of that interval is the gene's LOEUF score, 1.15, which puts it in group 5 of 6, group 1 being the genes least tolerant of losing a copy. Missense variants: 238 observed, 229.14 expected, observed/expected ratio (o/e) 1.04, 90% interval 0.93 to 1.16. Synonymous variants: 100 observed, 85.81 expected, observed/expected ratio (o/e) 1.17, 90% interval 0.99 to 1.38.
Gene-disease validity (ClinGen):
ClinGen rates the evidence that COX4I1 causes each of these diseases.
Leigh syndrome (autosomal recessive): Limited. A progressive neurological disease defined by specific neuropathological features associating brainstem and basal ganglia lesions.
mitochondrial disease (autosomal recessive): Limited.
Homologues: Orthologues: chimpanzee COX4I1 (100% identical), macaque COX4I1 (93% identical), pig COX4I1 (81% identical), rabbit COX4I1 (81% identical), guinea pig COX4I1 (80% identical), rat Cox4i1 (80% identical), mouse Cox4i1 (78% identical), dog COX4I1 (75% identical), tropical clawed frog cox4i1 (66% identical), zebrafish cox4i1 (64% identical), Drosophila melanogaster COX4 (34% identical), Drosophila melanogaster COX4L (33% identical), and 1 more. Paralogues in human: COX4I2 (52% identical).